BRAF (B-Raf proto-oncogene, serine/threonine kinase)
Diseases named in the same sentence as BRAF in open-access papers (continued):
Sharing a sentence is not in itself a finding about the gene and the disease.
melanoma (continued). "A375 is a malignant skin melanoma cell line that harbors an activating BRAF mutation and was chosen based on the observation that EZH2 GOF mutations have been shown to occur concurrently with BRAF mutations in melanoma." (PMID 25671303, 2015). "Two BRAF inhibitors, vemurafenib and dabrafenib, targeting the BRAF p.V600 mutated protein, have recently been shown to prolong the progression-free and/or the overall survival of BRAF V600-mutated advanced melanoma, as compared to dacarbazine." (PMID 26141748, 2015). "The BRAF gene is mutated in approximately 7 % of human cancers overall, specifically, 40 % to 60 % of malignant melanomas, 10 % to 15 % of colorectal cancers (CRCs), and 1 to 5 % of non-small cell lung cancers (NSCLC)." (PMID 26498038, 2015). "For example, the somatic BRAF V600E mutation, normally occurring in nevi and melanoma, can be oxidative stress-induced and loss of p16 expression, commonly observed in melanoma, leads to dramatic increases in ROS levels in cultured human melanocytes." (PMID 26064422, 2015). "Activative mutations of BRAF are the most prevalent genetic alteration in human melanoma, with ≥50% of tumors expressing the BRAFV600E oncoprotein." (PMID 27462428, 2015). "Here we report on the first prospective and multicenter study assessing in routine practice testing of BRAF V600 mutations in melanoma samples by HBM in molecular genetics laboratories in parallel with the cobas test, an approved and automated assay." (PMID 25789737, 2015). "MTF cultures from individual patients (5 of 8) contained melanoma-specific BRAF activating mutations." (PMID 26267609, 2015). "A375 cell lines are therefore a representative model of such melanoma subtype, since they show BRAF V600E mutation." (PMID 25474135, 2015). "Since the discovery of activating mutations in the BRAF oncogene and the stimulation of an immune-mediated antitumor response in melanoma, there has been remarkable progress in the development of targeted therapies for unresectable and metastatic melanoma." (PMID 25742310, 2015). "Under this concern, it is known that advanced anti-melanoma strategies are based on the usage of BRAF inhibitors, that selectively inhibit the proliferation of melanoma cells harbouring the BRAFV600E mutation." (PMID 26474275, 2015). "The most common gene mutation in melanoma is BRAF and NRAS which accounted for 50% and 20%, respectively; both mutations increase activity of the MAPK pathway." (PMID 26664783, 2015). "This study demonstrates multiple additional molecular alterations amongst BRAF mutation-positive patients with advanced melanoma who achieved a CR or PR on BRAF targeted agents." (PMID 25886620, 2015). "Patients with BRAF mutation-positive advanced melanoma respond well to matched therapy with BRAF or MEK inhibitors, but often quickly develop resistance." (PMID 25886620, 2015). "Increased cell proliferation, enhanced cell survival and tumorigenesis are associated with mutational activation of a serine/threonine kinase BRAF in approximately 60% of melanomas." (PMID 26299806, 2015). "BRAF protein was identified as a possible target for new therapies, given that mutated forms of the BRAF gene lead to unrestricted tumor growth in melanomas." (PMID 26705496, 2015). "For example, about half of melanomas show mutations in BRAF, making these cells sensitive to specific BRAF (Vemurafenib) and/or MEK inhibitors." (PMID 26513174, 2015). "Cancer-driving BRAF mutations (V600E/K) are found in 40-60% of melanoma patient tumors, and BRAF-inhibitor agents, dabrafenib and vemurafenib, have extended median patient survival by 5-6 months." (PMID 26262134, 2015). "The discovery of such somatic mutations in the BRAF gene has paved the way for developing targeted therapies in melanoma." (PMID 25789737, 2015). "Interesting CDK4 inhibition can induce irreversible cell cycle arrest and senescence in melanoma cells with BRAF mutations." (PMID 26236691, 2015).
melanoma (continued). "The evidence of BRAF mutated forms (above all BRAFV600E) in melanoma, papillary thyroid cancer and colorectal cancer have pushed the researchers to focus on this target." (PMID 26431495, 2015). "It has been previously proposed that BRAF mutated cancer cells either of melanoma or of thyroid or of colorectal origin, undergo increased ErbB3 protein expression consequent to transcripional activation." (PMID 26208478, 2015). "BRAF mutational status was also related to anatomical sites (p = 0.03): in our sub-group of patients BRAF mutations prevail in melanoma of trunk compared to melanoma of the hand and foot that were all wild type for BRAF." (PMID 26834525, 2015). "Another limitation of our study is incomplete data on both BRAF mutational status and ulceration in melanoma patients." (PMID 25815245, 2015). "MAPK signalling, which converges on ERK and is related to the single mutation in the BRAF protein, has been also reported as a relevant pathway involved in melanoma disease and progression." (PMID 26370966, 2015). "The vemurafenib-resistant melanoma cell line C3 SKMEL-239 produces BRAF exon 3^9 splicing and contains two intronic point-mutations at positions -435 (C-to-A) and -51 (C-to-G) from the BRAF intron 8 3′ splice site." (PMID 26697165, 2015). "We therefore conducted an immunohistochemical analysis to confirm the correlation between the expression levels of FOXM1 and the BRAF mutation status and/or the pAKT status in melanoma tissue specimens." (PMID 26640950, 2015). "Melanoma is an aggressive form of skin cancer, with mutations in BRAF and NRAS genes occurring in ~50% and ~15% of tumors respectively." (PMID 25544760, 2015). "The identification of molecular features associated with primary resistance to mutant BRAF targeting will enable identification of melanoma patients likely to fail treatment." (PMID 25742786, 2015). "In 2002, activating mutations in the gene encoding the serine/threonine kinase BRAF were identified by the Cancer Genome Project (Sanger Centre, UK) in a subset of human cancers, including about 50% of malignant melanomas." (PMID 25422355, 2015). "He started treatment with vemurafenib at 960 mg twice a day since a molecular analysis showed that his primary melanoma harbored a BRAF V600E mutation." (PMID 25962795, 2015). "This RAS-RAF-MEK-ERK pathway is constitutively activated in melanomas harboring mutations in oncogenes such as BRAF and NRAS, respectively mutated in about 50 % and 15 % of these tumors." (PMID 26204954, 2015). "After the discovery and characterization of BRAF mutations in human melanoma, vemurafenib, the first selective inhibitor for mutant BRAF, was developed and evaluated for a treatment option for patients with BRAF-mutated metastatic melanoma." (PMID 29061943, 2015). "Previous studies have reported a higher frequency of BRAF mutation in patients with malignant melanoma and thyroid cancer compared with patients suffering from other types of cancer." (PMID 25436010, 2015). "Melanoma associated genes were indentified (via key words: melanoma, BRAF, and MITF) which produced a refined gene list (n = 16) common to all." (PMID 25980496, 2015). "In particular acquisition of resistance of melanoma cells to BRAF inhibition was found to be associated with up-regulation of PD-L1 that was dependent on the MEK and PI3K pathways and activation of c-Jun and STAT3." (PMID 25844720, 2015). "The frequency of concomitant KRAS or NRAS mutations found in a BRAF-mutated tumor was 4 of 33 (12 %) in NSCLCs, 3 of 34 (8.8 %) in CRCs, or 3 of 67 (4.5 %) in melanomas." (PMID 26498038, 2015). "Mutation in the serine-threonine kinase BRAF was observed in close to 50 % of metastatic melanoma lesions, mostly of the valine to glutamine substitution in codon 600 (V600E)." (PMID 27508107, 2015). "Selective BRAF inhibitors such as vemurafenib and dabrafenib have shown high objective response rates of about 50 % in patients with BRAF(V600E) mutated (BRAFm) melanoma." (PMID 26617477, 2015).
melanoma (continued). "For example, PTEN loss was associated with resistance to RAFi (in BRAFV600E mutated melanoma) and as a result joint inhibition of BRAF and PI3K was proposed as a combination therapy." (PMID 26284497, 2015). "Constitutive activation of MAPK signaling plays an important role in the pathogenesis of human melanoma through activating mutations of BRAF (~60%) or NRAS (~15%) genes." (PMID 29061943, 2015). "In melanoma, the BRAF gene is mutated in 40–60% of cases; the most prevalent mutation (about 90% of cases) is represented by the replacement of glutamic acid with valine at codon 600 (BRAFV600E)." (PMID 26322273, 2015). "Tumor tissue from ten patients with advanced BRAF mutation-positive melanoma who achieved partial response (PR) or complete response (CR) on BRAF and/or MEK inhibitors was analyzed using next generation sequencing (NGS) assay." (PMID 25886620, 2015). "Molecular analyses have revealed that roughly 50% of melanomas harbor BRAF mutations, whereas NRAS mutations are observed in 15–20% of them." (PMID 26322273, 2015). "BRAF mutations were detected in 33 of 510 (6.5 %) NSCLCs, 34 of 275 (12 %) CRCs, and 67 of 152 (44 %) melanomas, including a melanoma specimen with both p.V600E (c.1799 T > A) mutation and p.S605I (c.1814G > T) occurring in the same allele." (PMID 26498038, 2015). "BRAF mutations were more common in melanoma, and a BRAF inhibitor has been approved for the treatment of melanoma." (PMID 25963410, 2015). "It is used in relapsed or refractory malignant melanoma following treatment with Ipilimumab or after treatment with Ipilimumab and a BRAF inhibitor in patients who carry a BRAF mutation at doses from 2 mg/kg to 10 mg/kg." (PMID 26060497, 2015). "Several studies have examined the presence of BRAF mutations in canine melanoma; however, only one study identified cBRAFV595E mutations in a small percentage of patients (6%)." (PMID 29061943, 2015). "The BRAF oncoprotein is found to be mutated in about half of malignant melanomas and other cancers, and is under intensive studies." (PMID 26429562, 2015). "Previously, we showed that Nodal expression in melanoma cells harboring the active BRAF mutation is unaffected when these cells are treated with a BRAF inhibitor (BRAFi)." (PMID 26460952, 2015). "We therefore examined the impact of PLX4032 and MEKi on RHOB expression in wild type BRAF melanoma cells harboring mutations in NRAS (WM1346 and SK-MEL2 cells), KIT (WM3211 cells) or KRAS (WM1791C cells)." (PMID 26098773, 2015). "In contrast to BRAF mutated melanoma, the kinase inhibitor imatinib has proven efficacy in patients with advanced melanoma harbouring KIT mutations." (PMID 26420268, 2015). "BRAF mutations are found in up to 60% of all melanomas and up to 10% of colorectal cancers, with BRAF mutant CRCs having a poorer prognosis to both wild type and RAS mutant tumours." (PMID 26149458, 2015). "There are more than ten types of BRAF mutation variants reported for malignant tumors such as bladder, melanoma, and PTC." (PMID 26273300, 2015). "More recently, a myriad of other targeted agents, such as erlotinib in EGFR-mutated non-small cell lung cancer and vemurafenib or dabrafenib in BRAF-mutated melanoma among others, have shown success." (PMID 26418953, 2015). "These metabolic effects were recently described in detail in the context of melanoma exposed to BRAF mutated inhibitors." (PMID 26713093, 2015). "First, we studied human melanoma cell lines with BRAF-V600E mutation (A2058, SK-MEL-28, A375, UACC62 and UACC257) and NRAS-Q61R mutation (SK-MEL-2)." (PMID 26158630, 2015). "Vemurafenib monotherapy was recently compared to the combination of dabrafenib plus trametinib in an open-label, randomized, phase III trial of previously untreated patients with unresectable stage IIIc or IV melanoma with BRAF V600E or V600K mutations." (PMID 26705496, 2015).
melanoma (continued). "The rapid technical advances in the molecular and genetic analysis of melanoma have led to the identification of mutations in the BRAF gene in melanoma and the development of targeted therapy for BRAF-mutant metastatic melanoma." (PMID 25962795, 2015). "It is noteworthy that benign melanocytic lesions also harbor BRAF mutations, in both humans and dogs, with frequencies similar to those of malignant melanoma." (PMID 29061943, 2015). "In particular EGFR inhibitors for EGFR-mutant NSCLC and the mutation-selective RAF and MEK inhibitors for BRAF-mutant melanoma are examples of successfully targeted therapy selection." (PMID 26435479, 2015). "In 2011 the trial of combination of vemurafenib and ipilimumab was launched so as to measure the efficacy of this combination in advanced melanoma with BRAF V600 mutation." (PMID 26171394, 2015). "Vemurafenib (Zelboraf) is a BRAF kinase inhibitor that blocks tumor growth by hindering cellular proliferation in melanoma cells with the BRAF mutation (U.S. Food and Drug Administration [FDA], 2011)." (PMID 26705496, 2015). "Targeting ‘driver’ mutations including EGFR in lung cancer and BRAF in melanoma resulted in great clinical success." (PMID 26544513, 2015). "In the present study we have investigated the mechanism underlying these two modes of PD-L1 expression in melanoma cells including cells that had acquired resistance to the BRAF inhibitor vemurafenib." (PMID 25844720, 2015). "The utility of pairing the molecular profiling of tumors and the application of targeted therapies is exemplified by the success of this approach in Her2-positive breast cancer and BRAF V600E mutated melanoma amongst others." (PMID 26015395, 2015). "BRAF V600E mutation (c.1799T>A, which results in p.Val600Glu amino acid change) is associated with thyroid, melanoma and colorectal cancers." (PMID 26258049, 2015). "If one looks at the early mutations that occur at the benign nevi stage, mutations in the BRAF gene are crucial (approximately half of all melanomas harbor a mutation in BRAF)." (PMID 26393652, 2015). "Because the oncogenic BRAF(V600E) mutation is observed in precancerous nevi it is thought to be a very early mutation in the development of melanoma." (PMID 26091525, 2015). "In the first part of this study, we used ultra-deep NGS to assess the BRAFV600 mutation status of primary melanomas and matched metastases and their influence on the outcome of BRAF inhibitor therapy." (PMID 26498143, 2015). "Therapies such as BRAF inhibitors have become standard treatment for melanoma patients whose tumors harbor activating BRAFV600 mutations." (PMID 25537510, 2015). "We found that combination treatment more effectively reduced phosphorylation of MEK1/2 and ERK1/2 in BRAF-mutated melanoma cells than individual agents." (PMID 26299806, 2015). "Both antibodies received FDA approval in 2014 for the treatment of advanced melanoma patients following progression after BRAF-targeted therapy (for those with BRAF V600-mutated melanoma) and after ipilimumab." (PMID 26518223, 2015). "One possible explanation is that the activation of the MAPK signalling pathway caused by BRAF increase promotes tumor cell growth and proliferation, thereby influencing melanoma progression from AJCC Stage I to Stage II." (PMID 25784655, 2015). "We also present the results of a genetic study on mechanisms of the BRAF mutant allele increase in melanoma." (PMID 26141748, 2015). "In human melanoma, the presence of BRAF mutations is associated with UV exposure, and tumors on mucosal sites or non-UV-exposed skin rarely possess the mutation." (PMID 29061943, 2015). "To date, in addition to vemurafenib, several drugs targeting the BRAF/MAPK pathway have demonstrated promising clinical efficacies for BRAF-mutated melanoma." (PMID 29061943, 2015). "BRAF mutations, primarily at codon V600, are the most prominent oncogenic event in melanoma, present in 40-50% of melanomas." (PMID 25537510, 2015).
melanoma (continued). "Since the discovery of BRAF mutations in melanoma in 2002, advances in molecular characterization of the disease have led to the development of specific BRAF inhibitors that are now available for the treatment of patients with metastatic melanoma." (PMID 26498143, 2015). "The study of dabrafenib and vemurafenib used as an adjuvant therapy in patients with BRAF V600 mutation positive melanoma who underwent surgical treatment is also in progress." (PMID 26171394, 2015). "Some of the well-established examples on oncogene addiction include amplification of HER2 in breast cancer, mutated EGFR in non-small cell lung cancer, mutated BRAF in melanomas and Bcr-Abl in chronic myeloid leukemia." (PMID 26204491, 2015). "Thyroid cancer showed an enrichment of the somatic melanoma driver mutation BRAF(p.V600E) that surpassed profiles of BRAF of any other tissue, while preserving mutually exclusive setting to RAS mutations." (PMID 25600636, 2015). "Other groups have shown that dabrafenib shows significant in vitro and in vivo anti-tumor effects in malignant melanoma with the BRAF V600E mutation." (PMID 26630652, 2015). "BRAF targeting TKIs (dabrafenib, vemurafenib) are approved for BRAF mutated malignant melanoma based on pivotal phase III trials." (PMID 26018876, 2015). "Among the technical issues related to BRAF mutation detection in melanoma, melanin content is overlooked." (PMID 26690267, 2015). "It was also shown that, in zebrafish, a hypomorphic mitfa mutation cooperates with oncogenic BRAF to promote superficial spreading melanoma." (PMID 25670789, 2015). "Vemurafenib and dabrafenib are the currently FDA-approved BRAF inhibitors that target these mutations for the treatment of melanoma." (PMID 27508107, 2015). "In contrast, primary or innate resistance is very uncommon, suggesting that without the selective pressure of long-term pathway inhibition most melanoma cells with BRAF mutations are sensitive to RAF/MEK/ERK pathway inhibition." (PMID 26236691, 2015). "Of all cancers, the BRAF(V600E) mutation is most prevalent in melanoma, being observed in about 50% of melanomas and a similarly large fraction of melanocytic nevi." (PMID 26091525, 2015). "In our study, 32.9 % of the patients (26/79) were concluded to have a BRAF-mutated melanoma (22.8 % (18/79) BRAFV600E, 6.3 % (5/79) BRAFV600Kand 3.7 % (3/79) BRAFV600R)." (PMID 26204954, 2015). "Since most melanomas are driven by an activating mutation at codon 600 of BRAF, we also analyzed its mutational status and CLDN11 methylation in MM cell lines." (PMID 26198249, 2015). "Studies on xenografts of a NRAS mutant human melanoma cell line indicated that shRNA knockdown of both BRAF and CRAF caused delay in the tumor formation." (PMID 25645078, 2015). "Similar effects both in vitro and in vivo were observed in 3D1 treated A375SM melanoma cells harboring the active BRAF(V600E) mutation compared to treatments with IgG control or a BRAF inhibitor, dabrafenib." (PMID 26460952, 2015). "As expected, according to the percentage of tumor cells in mutated BRAF melanomas, we observed a distinct distribution of the percentage of mutated allele." (PMID 26141748, 2015). "Mutations of the serine/threonine-protein kinase BRAF have been observed in 50% of malignant melanomas, and result in activation of mitogen activating protein kinase (MAPK) pathways." (PMID 25643913, 2015). "Exposure of BRAF mutated melanoma cells to clinically relevant doses of BRAFi leads to apoptotic cell death mediated by ER stress." (PMID 26713093, 2015). "The sample was enriched in patients with common mutations (e.g. BRAF-mutant melanoma), making the percentages of these patients higher than that which would be seen in the normal disease population." (PMID 26015395, 2015). "BRAF-activating mutation is a characteristic of malignant melanoma, and molecular-targeted therapy for BRAF has been developed." (PMID 26376781, 2015).